SEMA3A (semaphorin 3A)
Diseases named in the same sentence as SEMA3A in open-access papers (continued):
Sharing a sentence is not in itself a finding about the gene and the disease.
tumor (continued). "In sum, while in other tumor types, endogenous Sema3A levels are often suppressed and its reintroduction deploys inhibitory activity, autocrine Sema3A in GBM cells seems to act instead as promoter of migration via distinctive signaling cascades." (PMID 31052281, 2019). "The anti-tumor effects of Sema3A were directed toward the pruning and remodeling of abnormal blood vessels, and increasing their coverage with pericytes, all of which led to a stable vascular normalization." (PMID 30598022, 2018). "These preliminary findings encourage future research into the potential of semaphorins, particularly the combination of Sema3A+3F, in second-line cancer-suppressive treatments, to target endothelial cells and slow or restrict tumor growth." (PMID 29854302, 2018). "It has been recently reported that the expression of Sema3A from tumour cells is able to promote TAM accumulation inside the tumour, particularly in the avascular areas and required neuropilin-1 (NRP-1)-signaling cascade." (PMID 29507865, 2018). "Sema3A tissue level positively correlated with the tumor size, tumor numbers, tumor encapsulation, and tumor-node-metastasis staging." (PMID 30134791, 2018). "Sema3A, Sema3B and Sema3F have been long considered inhibitors of tumor growth and metastasis, even if it has been reported that Sema3E inhibits tumor growth but promotes metastasis." (PMID 30454024, 2018). "Their study showed that tumor cell-derived Sema3A inhibited proliferation and expansion of pro-tumor M2 macrophages, but increased the number of anti-tumor M1 macrophages." (PMID 30134791, 2018). "Mutant SEMA3A successfully normalized the vasculature, inhibited tumor growth, metastasis, and improved efficacy of chemotherapy in pancreatic cancer mouse models." (PMID 30532711, 2018). "To explore the mechanism responsible for the bidirectional effects of exogenous and tumour-derived Sema3A on the skeleton, we tested their effects on bone cell growth, differentiation and signalling." (PMID 29720701, 2018). "Another potential therapeutic target in anti-angiogenic tumor management is Sema3G which also shares NRP-1 receptor with Sema3A and Sema4A." (PMID 30598022, 2018). "The value of the Sema3A expression level in different types of cancer as a marker for a disease prognosis was discussed in a study designed to generate a safe tumor-suppressive Sema3A point mutant isoform." (PMID 30598022, 2018). "On the other hand, it has been reported that in hepatocellular carcinoma, Sema3A promotes tumor development and expansion." (PMID 30134791, 2018). "Engagement of Sema3A with Nrp1 and 2 and other receptors has shown to both enhance and reduce tumour cell motility and invasion in various preclinical models of cancer." (PMID 29720701, 2018). "In contrast to Sema3A tumor suppressor effects, Sema3E, which shares Plexin D1 receptor with Sema4A and Sema4D, consistently demonstrated the pro-tumoral effects." (PMID 30598022, 2018). "These researchers observed that tumor cell-derived Sema3A binds to NRP1 on macrophages and negatively regulates their proliferation, while favoring M1 macrophage proliferation." (PMID 29067024, 2017). "TAMs are retained inside the hypoxic areas to promote tumour angiogenesis by downregulation of neuropillin-1 and semaphorin 3A-mediated PlexinA1/A4 signalling." (PMID 28210073, 2017). "NRP1 is expressed on TAMs and is crucial for their migration to the hypoxic niche of the tumor in response to Sema3A." (PMID 29067024, 2017). "Because tumors can develop resistance toward the chemical drugs used against angiogenesis, Sema3A is highly significant to anti-tumor angiogenesis therapy." (PMID 28683823, 2017). "Collectively, these findings suggest that Sema3A plays a pathophysiological role in tumor progression." (PMID 28182100, 2017). "Inhibition of the Sema3A coreceptor, neuropilin-1, blocks the Sema3A-mediated effects on tumor metastasis." (PMID 28182100, 2017).
tumor (continued). "A significant correlation was observed between SEMA3A expression levels and pathological stage (P = 0.002), lymph node metastasis (P = 0.017) and tumor T-stage (P = 0.016)." (PMID 26755661, 2016). "Our results also indicated that Sema3A expression was clearly increased in tissues taken from patients who experienced tumor recurrence." (PMID 27351132, 2016). "The results indicated that Semaphorin 3A expression was up-regulated in metastatic cell lines and in samples from patients with tumor recurrence." (PMID 27351132, 2016). "Animal studies indicated that Semaphorin 3A overexpression enhanced tumor growth and lung metastasis." (PMID 27351132, 2016). "Gliomas have been shown to express high levels of TGF-β, VEGFA, HGF, and Sema3a, which promote tumor growth, neo-vascularization, invasiveness, and dispersal." (PMID 26755653, 2016). "TAMs' localization to hypoxic tumor areas is controlled by the Sema3A/neuropilin-1 signaling axis, leading to plexinA1/plexinA4-dependent VEGFR1 activation and promotion of tumor growth and metastasis." (PMID 27975071, 2016). "Sema3A, alone or in combination with TAMs, merits more study as a novel prognostic marker for patients who undergo tumor resection with curative intent." (PMID 27351132, 2016). "Class-3 Semaphorins, especially Semaphorin3A (SEMA3A), is involved in the suppression of tumor progression in various types of cancers through binding to its receptor neuropilins (NRPs)." (PMID 26755661, 2016). "Our results indicated that Sema3A is a key mediator of macrophage recruitment into the tumor microenvironment." (PMID 27351132, 2016). "Sema3A level was positively correlated with tumor size (p=0.005), tumor number (p=0.044), tumor encapsulation (p=0.046) and tumor-node-metastasis staging (p=0.018)." (PMID 27351132, 2016). "All the data above suggested that SEMA3A over-expression inhibited tumor growth and induced apoptosis in vivo." (PMID 26755661, 2016). "The inhibition of expression of Sema3A in the HCC cells reduced tumor volumes, pulmonary metastases, and TAM numbers." (PMID 27351132, 2016). "Taken together, our results indicate that SEMA3A serves as a tumor suppressor during HNSCC tumorigenesis and a new target for the treatment of HNSCC." (PMID 26755661, 2016). "Semaphorin-3A is a chemorepellent guidance protein that is crucial in regulating the tumor microenvironment." (PMID 24765144, 2014). "Several studies have demonstrated that overexpression of semaphorin-3A attenuates invasion and matrigel adhesion of tumor cells in certain types of cancer, including prostate and breast." (PMID 24765144, 2014). "It has been shown that the ratio of VEGF to semaphoring 3A (SEMA3A), an antiangiogenic factor, correlates with tumor recurrence better than VEGF expression alone." (PMID 25478572, 2014). "Semaphorin 3A (Sema3A) is expressed in endothelial cells, where it serves as an endogenous inhibitor of angiogenesis, and is lost during tumor progression." (PMID 24102047, 2013). "As an endogenous antiangiogenesis agent, Sema3A has been studied in tumor angiogenesis and metastasis for years, but its effects on retinal neovascularization are still unclear." (PMID 23825919, 2013). "Since the discovery of Sema3A, a variety of studies have reported its effects on neuronal cell migration, tumor metastasis, and vascular genesis." (PMID 23825919, 2013). "Semaphorin 3A is a secreted protein that regulates cell motility and attachment in axon guidance, vascular growth, immune cell regulation and tumor progression." (PMID 23469280, 2013). "Sema3A inhibits angiogenesis, migration of keratinocytes, proliferation of T cells, and migration of tumor cells." (PMID 23343469, 2013). "This work suggests that tumors can negate anti-tumor immune responses by secreting SEMA3A, although this requires confirmation in vivo." (PMID 22948112, 2012). "A significant difference in the expression of SEMA3A existed between normal and tumour tissues (P=0.025)." (PMID 22926477, 2012).
tumor (continued). "The ability of SEMA3A to inhibit tumour angiogenesis by competing with vascular endothelium growth factor (VEGF) for binding with NRP1 has been more intensively studied and confirmed." (PMID 22926477, 2012). "Current studies have shown that axonal sprouting inhibitor, semaphorin 3A (Sema 3A) acts as a potent suppressor of tumor angiogenesis in various cancer models." (PMID 22448259, 2012). "It was reported that endogenous sema3A expressed by U87MG cells promotes the dispersal of the tumor cells as a result of inhibition of cell adhesion." (PMID 22936999, 2012). "SEMA3A is particularly relevant to anti-tumor immunity, because tumors frequently produce this soluble mediator, which inhibits human T-cell proliferation and cytokine production." (PMID 22948112, 2012). "In another recent study, Sema3A role in tumor progression and in tumor angiogenesis was evaluated using three experimental approaches, using different systems for the release of the semaphorins." (PMID 24212788, 2011). "Sema3A, sema3D, sema3E and sema3G overexpression in breast cancer cells significantly inhibits the development of tumor in xenograft models and decreases the number of intra-tumor blood vessels, suggesting an anti-angiogenic role of these molecules." (PMID 24212788, 2011). "In conclusion, we have found for the first time that the semaphorins sema3A, sema3D, sema3E and sema3G possess anti-tumorigenic and anti-angiogenic properties similar to those displayed by the previously identified tumor suppressor sema3F." (PMID 18818766, 2008). "We have presented here for the first time evidence indicating that sema3D, sema3G sema3E and sema3A can significantly reduce the concentration of microvessels in tumors that develop from tumor cells that express these semaphorins." (PMID 18818766, 2008). "Notably, previous research has shown that SEMA3A, which functions as a tumor suppressor, is frequently downregulated in various malignancies, including ovarian epithelial carcinomas." (PMID 38541683, 2024). "However, when we adoptively transferred stimulated OT-I T cells into these mice, Sema3a KO tumor growth was significantly delayed compared to Sema3a OE tumors." (PMID 38609390, 2024). "However, the depletion of macrophages resulted in a significant greater benefit in terms of overall survival following chemotherapy for tumours with high expression of SEMA3A." (PMID 38670629, 2024). "Our study establishes SEMA3A as an inhibitor of effector CD8+ T cell tumour infiltration, suggesting that blocking NRP1 could improve T cell function in tumours." (PMID 38609390, 2024). "Given its impact on tumor cell behavior, SEMA3A expression may have implications for disease prognosis and treatment strategies." (PMID 38263416, 2024). "Conversely, SEMA3A knockout or overexpression in B16.F10.Ova cells was shown to have significant effects on T cell migration and control of tumor growth when treated with tumor-specific CD8+ T cells." (PMID 38609390, 2024). "Furthermore, SEMA3A expressing tumours (from FC1199 cells) colonised the liver parenchymal more efficiently than the knockout cells after intrasplenic injection." (PMID 38670629, 2024). "However, SEMA3A expression varies across cancer subtypes and can either be correlated with a better prognosis, by inhibiting tumor growth and angiogenesis, or induce cancer cell invasiveness and cancer progression." (PMID 38263416, 2024). "As opposed to the conditioned medium from Sema3a deficient cells, the conditioned medium from SEMA3A expressing tumour cells significantly induced Arg1 expression without eliciting Nos2 expression." (PMID 38670629, 2024). "In our study, we conducted an analysis of SEMA3A expression in both, tumor cells and vessels." (PMID 38263416, 2024). "However, a greater infiltration of CD8+T cells is observed in SEMA3Ahigh tumours on macrophages depletion, suggesting a potential chemoattractant role of SEMA3A for T cells." (PMID 38670629, 2024).
tumor (continued). "Furthermore, due to the anti-angiogenic effects of SEMA3A29, several groups have proposed utilizing SEMA3A to inhibit tumor growth." (PMID 38609390, 2024). "However, a correlation between SEMA3A expression and Ki67 level was found in the tumor cells (p = 0.0005, R Spearman 0.338)." (PMID 38263416, 2024). "Finally, the depletion of macrophages with a CSF1R monoclonal antibody improved gemcitabine antitumour activity, particularly for SEMA3A expressing tumours." (PMID 38670629, 2024). "We therefore decided to examine the role of SEMA3A in anti-tumor immunity more closely." (PMID 38609390, 2024). "Overall, Sema3a expressing cell lines (FC1199A and FC1245) generated larger tumours with a solid growth pattern as opposed to the cystic pattern observed for Sema3a deficient or low cells." (PMID 38670629, 2024). "To conclude, NR2F2‐AS1 may attenuate OSCC cell metastasis and angiogenesis of HUVECs and suppress tumor growth and metastasis in mice via the miR‐32‐5p/SEMA3A axis." (PMID 39177014, 2024). "Evodiamine, a natural anti‐tumour compound, inhibits the lactylation modification of hypoxia inducible factor 1 subunit alpha (HIF1a) by suppressing intracellular lactate production, thereby weakening HIF1a's inhibitory function on Sema3A." (PMID 39456119, 2024). "Therefore, we sought to investigate the role of tumour cells derived SEMA3A in pancreatic progression." (PMID 38670629, 2024). "Because SEMA3A mainly binds to these effector and tumor-specific T cells, this inhibitory mechanism is particularly important, and indicate that therapeutic avenues, for example use of antagonistic NRP1 antibodies, could improve anti-tumor immunity." (PMID 38609390, 2024). "SEMA3A overexpression was associated with an increase in the recruitment of CD49b+ NK cells and CD3+ T cells to the tumour and a higher ratio of CD8+ to CD4+ T cells, and with a significant reduction in tumour volume (61%) and weight (60%) compared to control tumours." (PMID 37685898, 2023). "However, when NRP-1 is downregulated in TAMs, SEMA3A/PlexinA1/PlexinA4 stops TAMs from migrating and inhibits their immunosuppressive and angiogenic properties, which impedes tumour growth." (PMID 37685898, 2023). "Furthermore, it has been found that Sema3A gene expression can be upregulated by inhibiting Galectin-1, a pro-tumor vascular factor." (PMID 38078001, 2023). "Apart from regulating the immune response, SEMA3A executes its tumour suppressor function within the cancer cells themselves by regulating downstream signalling through PTEN, FOXO3A and MelCAM, which have been reported to function as tumour suppressor genes themselves." (PMID 37685898, 2023). "This may suggest that Sema3A/NRP1/TGF-β axis-mediated signaling elicits protumorigenic effects by regulating tumor-autonomous proliferative pathways and the tumor microenvironment (TME)." (PMID 37788099, 2023). "These unhelpful effects of sunitinib were overcome with combined SEMA3A treatment, with the combination demonstrating not only a reduced tumour burden and reduced angiogenesis but also reduced cancer invasion into surrounding tissue, including lymph node and liver metastases." (PMID 37685898, 2023). "Experiments in RIP1-Tag2 mice have shown that the expression of semaphorin 3A (SEMA3A) is progressively lost during tumor progression and that the inhibition of SEMA3A during the angiogenic switch may enhance tumor formation." (PMID 36059642, 2022). "Furthermore, stilbenes influence Nuclear Factor 1C protein, a tumour suppressor that localizes heavily on the SEMA3A promoter." (PMID 36557789, 2022). "Sema3A expression is higher in hypoxic tumor single cell suspensions than in normoxic conditions." (PMID 36071472, 2022). "Another study has demonstrated that blockage of Sema3A/Nrp1 could also enhance anti-tumor response by increasing M1-Mφs and decreasing M2-Mφs in colorectal carcinoma." (PMID 35155237, 2022).
tumor (continued). "Furthermore, another study showed that HMGB1 silences a tumor growth and metastasis repressor semaphorin SEMA3A via directly binding to its genomic locus, promoting heterochromatin formation and decreased occupancy of acetylated histones." (PMID 35679251, 2022). "Sema3A is increasingly being recognized as a key suppressor of tumor growth and metastasis." (PMID 35347234, 2022). "During EMT, tumor cells lose the epithelial marker E-cadherin and gain mesenchymal markers, such as Snail1 and vimentin, and these effects are abolished by the overexpression of Sema3A." (PMID 35775491, 2022). "Of note, re-expression of SEMA3A by viral gene transfer during late stages of pancreatic endocrine tumorigenesis leads to normalization of the tumor vasculature, increased pericyte coverage and inhibition of tumor progression." (PMID 36059642, 2022). "Therefore, reprogramming TAM polarization from M2-Mφs to M1-Mφs by altering Sema3A expression can be another effective approach to enhance anti-tumor effects." (PMID 35155237, 2022). "UC shows a higher expression of Sema3A, and it correlates well with tumor stage and grade." (PMID 33546237, 2021). "Considering the broad relevance of Sema3A activity in various tumor types, this molecule could represent a promising tool for cancer treatment." (PMID 33537086, 2021). "It has been shown that semaphorin 3A (Sema3A) is expressed in ECs during angiogenesis, where it serves as an endogenous inhibitor of angiogenesis that is present in premalignant lesions and lost during tumor progression in human uterine cervical cancer." (PMID 34503252, 2021). "Neoplastic tissues expresses higher levels of Sema3A in correlation with tumor stage and grade." (PMID 33546237, 2021). "Semaphorin 3A (Sema3A) was shown to play a significant role in different neoplasms." (PMID 33546237, 2021). "Our data suggest that LMP1 induces the expression of Sema3A, which may promote tumor progression in NPC." (PMID 32192122, 2020). "Some reports suggest that Sema3A acts as a tumor suppressor in certain cancers." (PMID 32192122, 2020). "Whether Sema3A functions as a tumor suppressor or tumor promoter is still unclear and may be cancer specific." (PMID 32192122, 2020). "SEMA3A has been extensively studied and it shows both pro- and anti-tumour effects." (PMID 32241267, 2020). "Moreover, Sema3A can affect cell phenotype indirectly by interfering with tumor angiogenesis and the immune response." (PMID 32192122, 2020). "Similar to previous reports, we found that SEMA3A was either up- or down-regulated in different cancer types, but we only found SEMA3A associated with poor prognosis in a number of cancer types (SARC, LUAD, HNSC, LGG, KIRC, and KIRP), where the expression of SEMA3A in tumours were all up-regulated." (PMID 32241267, 2020). "Our results demonstrate primarily the response of GBM6, an EGFRviii tumor, in response to Sema3A." (PMID 33302912, 2020). "On the other hand, several reports suggest that Sema3A may be a potent tumor suppressor in oral and lung cancers." (PMID 32192122, 2020). "This study also supports our results that Sema3A expression leads to tumor progression." (PMID 32192122, 2020). "Taken together, our results demonstrate that SEMA3A serves as a tumor suppressor of OPC tumorigenesis and may become a new target for the treatment of OPC along with therapeutic HPV vaccine." (PMID 32842711, 2020). "In addition, high mobility group box-1 (HMGB1) binds to the sema3A genomic locus and inhibits sema3A expression, resulting in increased migration of tumor cells." (PMID 30696103, 2019). "Although promising, these in vivo findings leave open the question of whether local or systemic administration of the soluble forms of Sema3A, Sema3D, Sema3E, or Sema3F may recapitulate the tumor-suppressing effect of ectopically expressed molecules." (PMID 31052281, 2019). "The SEMA3A expression was influenced by tumor stage and gender of participants." (PMID 31205625, 2019).